LINC01993 (long independently transcribed non-coding RNA 1993)
Gene: Long non-coding RNA gene on chromosome 17 (78,261,349 to 78,278,492, reverse strand). Ensembl gene ENSG00000204277.
Diseases named in the same sentence as LINC01993 in open-access papers:
LINC01993 is named in the same sentence as 1 disease in open-access papers, as found by Europe PMC text mining. Sharing a sentence is not in itself a finding about the gene and the disease. The quoted sentences say what the papers report.
cancer (1 paper, 2021). A tumor composed of atypical neoplastic, often pleomorphic cells that invade other tissues. "It was found that 5 lncRNAs (CATIP-AS2, TTC3-AS1, LINC01993, LINC01564, and LINC02015) were upregulated in various types of cancers including GC." (PMID 34257651, 2021).